TNF (tumor necrosis factor)
Diseases named in the same sentence as TNF in open-access papers (continued):
Sharing a sentence is not in itself a finding about the gene and the disease.
injury (continued). "NF-κB activation during the process of alcohol-mediated liver injury might be caused by drug-metabolizing enzyme-induced oxidative stress, whereas IL-1β, TNF-α, and iNOS might be the primary NF-κB-inducing factors during immune-mediated liver injury." (PMID 31881060, 2019). "TNF-α and IL-1β are mainly from monocytes and macrophages in the acute and chronic liver injury and may trigger the production of many other proinflammatory cytokines and induce hepatocyte death through the recruitment of neutrophils." (PMID 29743924, 2018). "The results showed that taraxasterol could inhibit inflammatory cytokines TNF-α and IL-6 production in mice with ethanol-induced liver injury." (PMID 30344887, 2018). "Furthermore, aqueous extract of dandelion leaf have been reported to ameliorate oxidative stress by reducing TNF-α expression in carbon-tetrachloride induced liver injury or in LPS-induced acute lung injury." (PMID 28077102, 2017). "The present results exhibited that LPS induced inflammation and immune suppression in the lung via influencing IgM, IgG, IL-1β, IL-6, and TNF-α, while indirubin markedly reduced IgM abundances and IL-1β and TNF-α mRNA abundances in LPS-induced acute lung injury." (PMID 28525368, 2017). "The present data indicate that BMSCs may serve as the basis of a novel therapeutic approach for patients suffering from pulmonary complications after brain injury, based on the TNF-α inhibition, in future clinic practice." (PMID 26931747, 2016). "We speculated that the declined speed of damaging effect of TNF-α was faster than the protective effect during the process of persistently increasing Enbrel in the CCl4-induced acute liver injury." (PMID 26843922, 2016). "The plasminogen activator urokinase receptor, which was found to be significantly increased 1–3 h after trauma, has been described to be upregulated by IL-1β and TNF-α, both of which have been reported to be increased early following clinical and experimental blunt chest trauma." (PMID 26303896, 2015). "UTI, a urinary trypsin inhibitor, has been shown to possess anti-inflammatory properties and attenuate LPS-induced acute lung injury, inhibit systemic inflammatory responses resulting from pulmonary I/R and alleviate pulmonary I/R injury via the inhibition of TNF-α expression in rats." (PMID 25187844, 2014). "In addition, the administration of anti-HMGB1 neutralizing antibodies has been shown to preserve BBB integrity and suppress the expression of inflammatory molecules such as TNF-α in the case of brain injury." (PMID 23874584, 2013). "In this study MK-886 significantly reduced the elevation of IL-6 and TNF-α level in the shocked rats as compared with induced untreated group suggesting that MK-886 has protective effect in hemorrhagic shock-induced acute lung injury." (PMID 21649921, 2011). "In the present study, we provide the first evidence that in the DRG, PAFR is important in the pathogenesis of tactile allodynia, a major behavioral consequence of nerve injury, and are responsible for production of proinflammatory cytokines such as TNFα and IL-1β." (PMID 20454616, 2010). "In the present study, using the tunnel coloration we have clearly confirmed that TNF-α plays an important role in the induction of apoptosis during acute lung injury and that the treatment with etanercept and genetic inhibition of TNF-αR1 attenuates the degree of apoptosis." (PMID 17971210, 2007). "Targeting inflammatory pathways through IL-1β and TNF-α inhibitors has shown promise in reducing cardiovascular complications, and further exploration of immunomodulatory therapies may provide additional benefits in trauma-related myocardial dysfunction." (PMID 40710793, 2025). "In addition, we suggest that pretreatment with TNF-α and IL-1β directly enhances the immune regulation ability of hADSCs against hepatic inflammation and restrains the adverse consequence of cholestatic liver injury." (PMID 37095581, 2023).
injury (continued). "Results of the present study were similar to our prior study, which showed that LPS-induced acute lung injury mice administered Sanghuangporus sanghuang mycelium could significantly decrease concentrations of TNF-α, IL-1β, IL-6, and NO in bronchoalveolar lavage." (PMID 35111796, 2021). "Genes that encode inflammatory cytokines (such as TNF and IL1), chemokines (such as CCL2, CXCL1, CXCL2, and CXCL3) and cell proliferation-related proteins (such as CycD and CycE) were downregulated when Cyp2c29 was overexpressed in a mouse model of liver injury." (PMID 32587777, 2020). "In addition, IL-1β, IL-6, TNFα, and the chemokines CCL5 and CXCL2 (which were all upregulated by LPA in primary microglia) are implicated as modulators of the neuroinflammatory response during traumatic brain injury where LPA levels are increased." (PMID 27565558, 2016). "Also, these results suggest that halothane exposure may increase the risk of alcohol-induced heart injury, since halothane pre-treatment potentiates the HEC TNF-α release measured following both MAA-Alb and LPS stimulation." (PMID 15826301, 2005). "The overlapping roles of cytokines, particularly IL-3, IL-6, IL-10, IL-17, TNF-α, and TGF-β, suggest significant crosstalk between pathways in radiation-induced lung injury (RILI) and immunotherapy-related lung injury (IRLI)." (PMID 40299683, 2025). "Liu and collaborators showed that 4-HPA was able to reduce the levels of the pro-inflammatory cytokines TNF-α, IL-1β, IL-6, and HIF-1α and prevent lung oedema in a rat model of acute lung injury." (PMID 39000542, 2024). "Importantly, human UC-MSCs pretreated with a cocktail containing GC, IFNγ, and TNFα could significantly enhance the therapeutic effect of human UC-MSCs in an acute lung injury mouse model, as reflected by reduced infiltration of immune cells and down-regulation of iNOS in macrophages in the lung." (PMID 38238297, 2024). "Combining ARG with L. plantarum significantly inhibited TNF-α, which can be assumed as a chief mechanism for its protective role in PDC-induced acute hepatic and kidney injury." (PMID 37427328, 2023). "Therefore, by silencing TNF‐α, NT‐3 and TRKC can be upregulated to promote the recovery of neurological function and other pathological lesions after HI injury, which maybe improve the mental retardation and movement disorders caused by brain injury." (PMID 38680513, 2023). "For example, NFATc3 transcriptionally regulates the expression of tumor necrosis factor alpha (TNF-α), promoting the progression of LPS-induced acute lung injury." (PMID 36825443, 2023). "TNF-α/HMGB1 (high mobility group box 1) inflammation signaling pathway regulates pyroptosis during acute liver failure and kidney injury." (PMID 35646948, 2022). "In our study, the concentrations of these pro-inflammatory biomarkers (TNF-α, IL-6, IL-1β, and NF-κB) were markedly elevated in lung tissue homogenate of the BLM mice model of acute lung injury." (PMID 35808662, 2022). "On the contrary, using two different models of perinatal brain injury, CGS21680 produced a partial increase of some microglial cytokines such as IL-1β and TNF-α, as well as an increase of iNOS." (PMID 35387355, 2022). "In this study, the levels of the pro-inflammatory markers (IL-6, IL-1β, TNF-α, and NF-kB) were high in the pulmonary tissues of the BLM-induced model of acute lung injury." (PMID 36500388, 2022). "A previous study found that peripheral blood leukocytes from trauma patients with the TLR2 rs3804099 CC genotype produce greater amounts of IL-10, IL-8, and TNF-α than those having the TT genotype, after bacterial lipoprotein stimulation." (PMID 32576967, 2020). "The results showed that Emo could not reduce the pulmonary inflammatory infiltration and lung injury score in the rat model of acute lung injury with granulocyte deficiency, nor could it reduce the levels of inflammatory factors TNF-α and IL-1β in lung homogenate." (PMID 32782444, 2020).
injury (continued). "It has been previously shown that C1-inhibitor protects from focal brain trauma in mice by reducing thrombo inflammation and diminishing upregulation of proinflammatory factors, such as CCL2, CCL3, IL-beta, and tumor Necrosis Factor alpha (TNF-α)." (PMID 33375205, 2020). "Our results showed that CD significantly reduced synthesis of TNF-α, IL-1β, and IL-6 in serum, indicating that CD treatment alleviated the inflammatory responses due to APAP-induced liver injury." (PMID 33364966, 2020). "WPPs can alleviate liver injury by regulating the serum levels of IL-6, IL-12, TNF-α, and IFN-γ in mice with liver injury, and the effect is similar to that of silymarin." (PMID 31683564, 2019). "TNF-α and IL-1β, two major proinflammatory cytokines, play a major role in exacerbating ICH-induced brain injury." (PMID 30498516, 2018). "In this study, we observed increases in the activation of TNF-α and p-JNK in rats with MCAO-induced brain injury." (PMID 28168001, 2017). "Taken together, both studies indicate that the expression of IL-1β, TNF-α, IL-8, and MCP-1 can be upregulated in acute lung injury in both mice and guinea pigs." (PMID 27446082, 2016). "In the present study, the time-course changes in the expression levels of plasma TNF-α and the corresponding TNFR1 (p55) and TNFR2 (p75) receptors were examined in 60 trauma patients." (PMID 25364459, 2014). "In chronic liver injury, injured and damaged cells such as hepatocytes and Kupffer cells release various profibrotic cytokines, for example, PDGF, TNF-α, and TGF-β1." (PMID 24860243, 2014). "Tumor necrosis factor (TNF-α)-α is a central proinflammatory cytokine, and it has been suggested that it is important in the development of alcohol induced liver injury." (PMID 24090365, 2013). "In a previous porcine acute lung injury model, LMWH was shown to attenuate neutrophil adhesion and TNF-α activity." (PMID 19580651, 2009). "BAL levels of CXCL1, CXCL2, IL-1β, TNFα and TGFβ were increased during the early phase, while IGF-1 levels were significantly increased in the later phase, suggesting that IGF-1 is involved in the resolution processes of acute lung injury." (PMID 41431237, 2026). "The TNF-α/NF-ĸB pathway is a crucial mediator of inflammatory and immune responses, while EMT is an important cellular programme that regulates embryogenesis and wound healing processes, and it is commonly active after kidney injury." (PMID 37104179, 2023). "The results of the KEGG analysis illustrated that the apoptosis signaling pathway, IL17 signaling pathway, TNF signaling pathway, and NOD-like receptor signaling pathway might be the main signaling pathways of KP-induced liver injury." (PMID 36518852, 2022). "Previous studies have suggested that the levels of tumor necrosis factor α (TNF-α), nuclear factor (NF-κB), interleukin 1β (IL-1β), and IL-6 increase in the bronchoalveolar lavage fluid of experimental rats with acute PQ-induced lung injury." (PMID 34580234, 2021). "LEO reduced BUN and Scr levels and downregulated TNF-α, IL-1, IL-6, IL-8, and kidney injury molecule-1 (KIM-1) expression by inhibiting the ROS-mediated NF-kB signaling pathway in a mouse model of lipopolysaccharide (LPS)-induced renal injury." (PMID 34437444, 2021). "More patients with liver injury than without had increased serum IL-2R, TNFα, ferritin, hsCRP, PCT, ESR, γ-GT, and LDH." (PMID 33026573, 2020). "This compound inhibited LPS-stimulated TNF-α release by intraperitoneal macrophages, the level of TNF-α in bronchoalveolar lavage fluid (BALF) in LPS-induced lung inflammation, and in liver in LPS-induced immunological liver injury." (PMID 32731392, 2020). "Other examples include Campath H-1 targeting CD52 on lymphocytes and monocytes with resulting elevated levels of TNF-α, IFN- ү, and IL-6; rituximab (anti-CD20) resulting in rapid increases in TNF-α and IL-6; and visilizumab (anti-CD3) induced cytokine release syndrome resulting in liver injury." (PMID 30469350, 2018).
injury (continued). "In sharp contrast to the steep increase in hepatic expression of IL-1β, IL-6, TNF-α and MMP-13 in the context of fulminant liver injury induced by D-GalN/LPS, the fibrotic mice were highly resistant to this attack, showing significantly less induction of inflammatory cytokines and MMP." (PMID 28874845, 2017). "But consistently down-regulated TNF-α level seems not a good choice for the treatment of acute liver injury." (PMID 26843922, 2016). "We also found that OMT could suppress the synthesis of tumor necrosis factor –alpha (TNF-α), interleukin-1beta (IL-1β) and interleukin-6 (IL-6) after traumatic brain injury via NF-κB pathway." (PMID 24250585, 2013). "Later during the posttrauma period (i.e., more than 6 days after the injury), the monocytes of alcohol-consuming trauma patients produce higher TNF-α levels than the monocytes of non-alcohol-consuming trauma patients." (PMID 15706761, 1997). "In any case, we can speculate that brain trauma did not modulate TNF-α in APP mice, at least at this presymptomatic stage." (PMID 38992700, 2024). "Therefore, excessive pro-inflammatory cytokines, such as IL-1β, IL-6, and TNFα, are considered to be the precursors of APAP-induced liver injury, and these pro-inflammatory cytokines are considered to affect the process of APAP-induced liver injury." (PMID 34639126, 2021). "Also, it has been shown that brain injury leads to increased activity of vagal nerve parasympathetic fibers, which in turn leads to downregulation of TNF-α production through the cholinergic pathway without affecting IL-10 production." (PMID 33237337, 2020). "CCl4-induced increases in TNF-α and α-SMA mRNA expression were suppressed by clodronate liposomes, as were hepatocyte ROS levels and oxidative stress, implicating the involvement of macrophages in HSC activation, increased hepatocyte ROS, and oxidative stress during acute liver injury." (PMID 33168815, 2020). "Therefore, TNF-α did not increase at the time when circulating histone H3 increased and kidney injury occurred." (PMID 31971961, 2020). "However, the levels of hepatic TNF-α, IL-1β, IL-4, IL-6, and TGF-β1 were significantly lower in rats with 2-AAF/PH-induced liver injury treated with Pue and RAPA than in untreated rats with liver injury, and IL-10 expression was higher." (PMID 30405406, 2018). "The inhibition of TNF-α, IL-1β, and IL-6 production by AVA might occur through pathways that converge on NF-κB activation because they can regulate cytokine production in LPS-induced acute lung injury." (PMID 29483931, 2018). "Furthermore, in a recent study from our laboratory, we found that TNF is only increased in rats subjected to a combined diffuse brain injury and hypoxia, but not in diffuse brain injury alone." (PMID 23459929, 2013). "They observed no changes in TNF, IFN-γ, MIP-1α, and MIP-1β levels in healthy volunteers or trauma patients but did note an increase in IL-8 levels as well as small decreases in IL-6, IL-10, MCP-1, and IP-10 in trauma patients only." (PMID 39480839, 2024). "Administration of preconditioned MSCs led to improved lung elastance and reduced levels of TNF-α and CXCL2 in the bronchoalveolar lavage fluid (BALF) of experimental ventilator-induced lung injury." (PMID 37007034, 2023).
multiple sclerosis (332 papers, 2007 to 2026). A progressive autoimmune disorder affecting the central nervous system resulting in demyelination. "Tumor necrosis factor alpha (TNFα) is a key cytokine involved in the inflammatory and neurodegenerative processes underlying multiple sclerosis (MS)." (PMID 41480143, 2025). "NF-κB activation in turn upregulates the expression of several genes implicated in the pathogenesis of multiple sclerosis, such as TNFα, iNos and IL1α/IL1β." (PMID 37999377, 2023). ": Multiple sclerosis (MS) is characterized by the destruction of the blood–brain barrier, loss of myelin sheath, and contribution of inflammatory interleukins such as TNF‐alpha, interleukin‐17, and interleukin‐6." (PMID 36582052, 2023). "Some of these miRNAs, such as miR-181a, have been linked to the pathogenesis of multiple sclerosis and TNF-α signaling, or miR-125 that controls functional synaptic integration and is involved in the modulation of innate immune signaling." (PMID 30374194, 2018). "Tumor necrosis factor (TNF) is associated with several neurodegenerative disorders including multiple sclerosis (MS)." (PMID 29690885, 2018). "Other data, in patients with multiple sclerosis, point toward the enhancement of the interaction between the receptor and its ligand by the R92Q variant, resulting in the potentiation of TNF-mediated pathways." (PMID 28396659, 2017). "In previous studies, TNFα, IL-1β, and IL-6 have been implicated as mediators of multiple sclerosis pathology." (PMID 23861993, 2013). "It has been shown in a mouse model of multiple sclerosis, that prolonged exposure to TNF-α from microglia, for example, can cause degeneration of the synapse." (PMID 22558223, 2012). "In murine T-cell-mediated demyelinating disease model of multiple sclerosis, venlafaxine significantly ameliorated clinical symptoms of the disease in association with a reduction of IL-12, TNF-α and IFN-γ." (PMID 23204981, 2012). "Various demyelinating disorders such as optic neuritis, multiple sclerosis, transverse myelitis, and Guillain–Barré have been reported in association with TNFα antagonist therapy." (PMID 22271346, 2012). "Excess TNF has been implicated in the pathophysiology of multiple sclerosis since the late 1980s." (PMID 40869160, 2025). "However, it should be borne in mind that TNF-α antagonists can increase disease activity in multiple sclerosis which emphasizes the necessity of a proper diagnostic differentiation of the conditions." (PMID 39812656, 2025). "A variety of manifestations of demyelinating disorders are associated with anti-TNF-α therapy and include, in descending order, optic neuritis, multiple sclerosis, demyelinating neuropathy, Guillain-Barre syndrome (GBS), and transverse myelitis, all of which have a fairly low incidence." (PMID 39078559, 2024). "In another clinical study on multiple sclerosis (MS) patients, 4 weeks of Crocin treatment induced a significant reduction in the levels of important pathogenic factors in MS, including lipid peroxidation, DNA damage, serum TNF-α, and IL-17 levels." (PMID 39850606, 2024). "However, a wide range of more severe neurological disorders has been associated with TNF-α inhibitors, including Guillain–Barre syndrome, peripheral neuropathies, multiple sclerosis, optic neuritis and acute transverse myelitis." (PMID 36836166, 2023). "The multiple sclerosis-TNF association was established by both HETIO and Pharos." (PMID 34283031, 2021). "The top-ranked answer set had 858 PubMed publications, contributed by OmniCorp, supporting the association between multiple sclerosis and TNF, and 44 PubMed publications, again contributed by OmniCorp, supporting the association between carbon monoxide and TNF." (PMID 34283031, 2021).